ATG16L1 (autophagy related 16 like 1)
Diseases named in the same sentence as ATG16L1 in open-access papers (continued):
Sharing a sentence is not in itself a finding about the gene and the disease.
liver fibrosis (3 papers, 2022 to 2024). "In the current research, by employing myeloid-specific Atg16l1ΔMφ mice, we have discovered a close association between the deficiency of macrophage Atg16l1 and the exacerbation of liver fibrosis damage." (PMID 39629085, 2024). "To assess the effect of macrophage ATG16L1 on the progression of liver fibrosis, we generated myeloid-specific Atg16l1-deficient (Atg16l1ΔMφ) and Atg16l1-proficient (Atg16l1FL/FL) mice." (PMID 39629085, 2024). "The present study aims to elucidate the functional role and underlying mechanisms of macrophage ATG16L1 in liver fibrosis, thereby providing novel therapeutic targets and theoretical foundations for clinical interventions." (PMID 39629085, 2024). "Currently, the precise mechanisms underlying the regulation of liver inflammation by ATG16L1 during liver fibrosis remain unclear." (PMID 39629085, 2024). "The current understanding of how macrophage ATG16L1 regulates liver inflammation in the context of liver fibrosis is unclear." (PMID 39629085, 2024). "In summary, these findings highlight the therapeutic potential of myeloid-specific Atg16l1 in alleviating inflammatory signaling, hepatocyte apoptosis, and HSCs activation, thereby presenting a promising avenue for intervention in liver fibrosis." (PMID 39629085, 2024). "First and foremost, our study commenced with clinical samples to analyze the expression levels of ATG16L1 in liver fibrosis." (PMID 39629085, 2024). "The findings highlight the potential therapeutic implications of targeting macrophage Atg16l1 or its downstream signaling pathways in the context of liver fibrosis." (PMID 39629085, 2024). "Given the pivotal role of TGF-β1 in the activation of hepatic HSCs during liver fibrosis, we developed a targeted culture system for HSCs to explore the potential influence of macrophage Atg16l1 on the activation of HSCs through the TGF-β1 signaling axis." (PMID 39629085, 2024). "We aimed to determine which of these macrophage subtypes predominantly mediated the function of macrophage Atg16l1 in the context of liver fibrosis." (PMID 39629085, 2024). "Employing RNA sequencing, we sought to elucidate the mechanisms of macrophage ATG16L1 in liver fibrosis by identifying critical signaling pathways." (PMID 39629085, 2024). "In conclusion, our study identifies macrophage Atg16l1 as a key regulator in liver fibrosis, with its deletion leading to enhanced inflammation and hepatocyte apoptosis." (PMID 39629085, 2024). "Atherogenic and high-fat diet-induced liver fibrosis mouse models display reduced C/EBPα and Atg16L1 expressions and increased liver fibrosis, while reversing high C/EBPα levels using peretinoin (an acyclic retinoid) increases autophagy activity." (PMID 36299447, 2022).
lung carcinoma (3 papers, 2012 to 2022). "Knockdown of the autophagy regulatory, ATG16L1, re-sensitized lung cancer cells to cancer therapies following TGF-β-induced resistance, implicating autophagy as a TGF-β-mediated chemoresistance mechanism." (PMID 30736412, 2019). "Interestingly, we found that ARHGs with active copy number increase (e.g. MYC, EIF4EBP1, EGFR) and ARHGs with active copy number loss (e.g. ATG16L1, MTOR, ULK1) also showed high expression in lung cancer tissues." (PMID 35333893, 2022). "Indeed, resistance to erlotinib is common in lung cancer, and ATG16L1 knockdown re-sensitized cells to increased EMT-induced erlotinib resistance." (PMID 30736412, 2019).
staphylococcus aureus infection (3 papers, 2018 to 2023). An infectious process in which the bacteria Staphylococcus aureus is present. "Endogenous TMEM59 interacts with ATG16L1 and mediates autophagy in response to Staphylococcus aureus infection." (PMID 37511481, 2023). "It has been demonstrated to bind ATG16L1 and mediate autophagy during Staphylococcus aureus infection." (PMID 29921667, 2018).
thyroid cancer (3 papers, 2019 to 2024). "Five hundred and sixty-seven miRNAs associated with nine autophagy proteins (ULK1, ATG16L1, MAP1LC3B, PRKAA1, ATG12, ATG 14, ATG5, mTOR and BECN1) were identified, of which sixty-two are accompanied by thyroid cancer, and only miR-125b is associated with the autophagy modulation in this pathology." (PMID 36980957, 2023).
Atrophic Gastritis (2 papers, 2023 to 2024). "We have reported that the G/G genotype of rs6431659 in ATG16L1 could be a good biomarker for detecting future severe atrophic gastritis." (PMID 38276136, 2024).
Buruli ulcer (2 papers, 2021 to 2023). "Recent genetic studies showed the protective effect of the minor allele G of ATG16L1 (rs2241880) from the ulcer phenotype in Buruli ulcer." (PMID 34552591, 2021). "In addition, several autophagy genes, including PRKN, NOD2, and ATG16L1, are related to susceptibility to severe Buruli ulcer." (PMID 34552591, 2021). "Importantly, the missense variant T300A (rs2241880) of the ATG16L1 gene is associated with the development of Buruli ulcer." (PMID 34552591, 2021). "However, it is still unclear whether a certain allele of ATG16L1 (T300A) functions in the suppression of autophagy against M. ulcerans to confer host protection against Buruli ulcer." (PMID 34552591, 2021). "Moreover, a specific allele of the ATG16L1 gene (rs2241880), producing a nonfunctional protein that impairs autophagy, has been associated with protective effects against Buruli ulcer." (PMID 37428812, 2023).
chordoma (2 papers, 2021). Chordomas are rare malignant tumors arising from embryonic remnants of the notochord in axial skeleton. "In contrast to normal notochords, autophagic factors such as LC3B and ATG16L1 are often present in chordomas, associated with a strong and diffuse expression of p62, suggesting a blocked autophagic flow." (PMID 33946484, 2021). "We show that autophagic factors, such as LC3B and ATG16L1, are often present in chordomas, associated with a strong and diffuse expression of p62, suggesting a blocked autophagic flow, in contrast to normal notochords." (PMID 33946484, 2021). "Similarly, the autophagy-related 16‐like 1 (ATG16L1) protein was expressed in most tumors, further supporting the presence of autophagic factors in chordoma tissues." (PMID 33946484, 2021). "Additionally, a recent IHC analysis showed positive expression of autophagic markers LC3B, P62 and ATG16L1 in chordoma compared with normal notochords, which revealed the potential oncogenic role of autophagy in chordoma." (PMID 34668612, 2021).
chronic obstructive pulmonary disease (2 papers, 2020 to 2024). A chronic and progressive lung disorder characterized by the loss of elasticity of the bronchial tree and the air sacs, destruction of the air sacs wall, thickening of the bronchial wall, and mucous accumulation in the bronchial tree. "In addition, autophagy is related to chronic obstructive pulmonary disease (COPD), and one polymorphism of an autophagy gene (Atg16L1) is linked to a more than 3-fold increased risk of COPD." (PMID 39441839, 2024).
coronary artery disease (2 papers, 2021). "We speculate that mutations in the ATG16L1 gene promoter may lead to abnormal gene expression, and this may play an important role in the occurrence and development of coronary heart disease and AMI." (PMID 34220924, 2021).
E. coli infection (2 papers, 2020 to 2022). "Collectively, our data indicate that Z. morio hemolymph limits detrimental inflammatory responses partly by regulating the NLRP3 inflammasome pathway through ATG5/ATG16L1-mediated autophagy pathway during E. coli infection." (PMID 36362066, 2022). "However, E. coli infection reduced ATG5 and ATG16L1 expression levels, further decreasing activity of autophagy, which mainly manifested as increased P62 expression level and decreased LC3A/B-II expression level." (PMID 36362066, 2022). "In the present study, a PMEC model of E. coli infection was established to test the hypothesis that L. johnsonii L531 attenuates E. coli–induced inflammation and cell damages by restricting NLRP3 inflammasome activity and promoting ATG5/ATG16L1–mediated autophagy in PMECs." (PMID 32823867, 2020).
epilepsy (2 papers, 2021 to 2024). A brain disorder characterized by episodes of abnormally increased neuronal discharge resulting in transient episodes of sensory or motor neurological dysfunction, or psychic dysfunction. "A study reported that increasing ATG16L1 levels through antagomir-223 treatment alleviated epilepsy in KA-treated mice, suggesting the microRNA-223/ATG16L1 pathway may offer a novel treatment option for TLE." (PMID 40217519, 2024). "Treatment with antagomir 223 alleviated epilepsy, prevented abnormalities in EEG recordings and increased the ATG16L1 and LC3 levels in KA-treated mice." (PMID 34381417, 2021).
fibrosis (2 papers, 2022 to 2024). the formation of excess fibrous connective tissue in an organ or tissue in a reparative or reactive process. "Clinical liver tissue specimens from patients with fibrosis were collected, and the expression levels of ATG16L1 in liver tissues were assessed using methods such as quantitative reverse transcription PCR, western blot, H&E staining, immunohistochemistry, and immunofluorescence." (PMID 39629085, 2024). "In addition, C/EBPα can regulate hepatic fibrosis through autophagy, with a recent study demonstrating that autophagy-related 16 like 1 (Atg16L1) is a target gene of C/EBPα in hepatocytes." (PMID 36299447, 2022).
head and neck squamous cell carcinoma (2 papers, 2014 to 2017). A squamous cell carcinoma that arises from any of the following anatomic sites: lip and oral cavity, nasal cavity, paranasal sinuses, pharynx, larynx, and salivary glands. "MiR-630 was also found to be upregulated in head and neck squamous cell carcinoma after cisplatin treatment and can modulate the protein expression of ATG5, ATG6/BECN1, ATG10, ATG12, ATG16L1 and UVRAG." (PMID 24621930, 2014).
influenza infection (2 papers, 2018 to 2025). "Our previous study on the ATG16L1 protein reported that the WD and linker domains are essential in restricting lethal influenza infection." (PMID 40143422, 2025). "In this study, using our ATG16L1 mutants, we have now revealed M2 protein‐dependent activation of non‐canonical autophagy during influenza infection." (PMID 29317426, 2018).
ovarian carcinoma (2 papers, 2022 to 2024). A malignant neoplasm originating from the surface ovarian epithelium. "Transcriptomic analysis of SKOV3 ovarian cancer cells treated with LPA indicated that GNA12 drives the decreased expression of ATG16L1, a protein involved in autophagosome formation." (PMID 39513923, 2024). "ATG16L1 has been reported to promote tumorigenesis in ovarian cancer by activating the PI3K/AKT/mTOR pathway." (PMID 35524319, 2022). "We have also reported that LPA downregulates the transcription of ATG16L1 in ovarian cancer cells." (PMID 39513923, 2024).
periodontitis (2 papers, 2023). An acute or chronic inflammatory process that affects the tissues that surround and support the teeth. "A study showed that vitamin D supplementation enhanced autophagy by upregulating the expression of these proteins in PBMCs and upregulating the expression of ATG5 and ATG16L1 in gingival tissue from patients with periodontitis." (PMID 36782172, 2023). "Our previous clinical study of periodontitis patients demonstrated decreased expression levels of the autophagy-related proteins ATG5-12 conjugates, ATG16L1 and ATG7, at the protein and mRNA levels." (PMID 37764988, 2023). "For example, peripheral blood mononuclear cells (PBMCs) from patients with periodontitis showed significantly downregulated levels of the autophagy-related proteins ATG5-12 conjugate, ATG16L1, and ATG7." (PMID 36782172, 2023). "Interestingly, Vit D supplementation rescued autophagy in periodontitis patients, and increased the expression of Beclin1, ATG5-12 conjugate, ATG16L1 and ATG7." (PMID 37764988, 2023).
plaque psoriasis (2 papers, 2017 to 2025). "Research has indicated that polymorphisms in the ATG16L1 gene are associated with an elevated risk of developing plaque psoriasis, and that ATG16L1 expression is augmented in the dendritic cells of patients with psoriatic arthritis." (PMID 39846685, 2025).
triple-negative breast carcinoma (2 papers, 2017 to 2021). An invasive breast carcinoma which is negative for expression of estrogen receptor (ER), progesterone receptor (PR), and human epidermal growth factor receptor 2 (HER2). "Even more, we observed that increases in the expression of autophagy markers ATG16L1 and LC3-B were associated with poor relapse-free survival in triple negative breast cancer patients." (PMID 33572239, 2021). "In TCGA data set, the gene expression of BECN1, ATG16L1 or SQSTM1 were markedly lower in triple-negative breast cancers (n=82) compared with other subtypes (n=391)." (PMID 28628113, 2017). "Immunohistochemical staining of consecutive sections of triple-negative breast cancer specimens revealed that tumor tissues expressed lower levels of BECN1, ATG16L1 and SQSTM1 than normal tissues." (PMID 28628113, 2017).
urinary tract infection (2 papers, 2018 to 2022). "ExPEC can actively exploit autophagy to facilitate its urinary tract infection, and a key autophagy protein Atg16L1 deficiency confers protection host against ExPEC infection." (PMID 29719540, 2018). "Although mechanistically distinct from how autophagy deficiency in the urothelium is protective, myeloid-specific deletion of ATG16L1 strongly enhances resistance to urinary tract infection by UPEC." (PMID 37425656, 2022).
acute pancreatitis (1 paper, 2025). An acute inflammatory process that leads to necrosis of the pancreatic parenchyma. "We applied this model to WT and to WDD and LNCA-deficient ATG16L1[E230] mice; acute pancreatitis was induced in both types of mice." (PMID 39216469, 2025). "Notably, in contrast to the caerulein model, there were no resolvable differences in any of the parameters characterizing the severity of experimental acute pancreatitis between WT and ATG16L1[E230] mice in the FAEE model." (PMID 39216469, 2025). "Here we report that the deletion of WDD (attained in ATG16L1[E230] mice) eliminated LNCA, aggravated caerulein-induced acute pancreatitis and suppressed the fast trypsin degradation observed in both a rapid caerulein-induced disease model and in caerulein-treated isolated pancreatic acinar cells." (PMID 39216469, 2025).
arteritis (1 paper, 2020). An inflammatory process affecting an artery. "The persistent downregulated ATG16L1 mRNA level in KD patients may contribute towards the marked chronic inflammation in arteritis." (PMID 33020418, 2020).
asthma (1 paper, 2020). "Previous studies have shown that ATG5 is involved in the autophagosome formation, which would form complex with ATG12 and ATG16L1, in patients with refractory asthma." (PMID 33643037, 2020).
Autoimmunity (1 paper, 2018). The occurrence of an immune reaction against the organism's own cells or tissues. "Several research groups have implicated the role of ATG5, ATG7, and ATG16L1 in keratinocytes, melanocytes, and immune cells in autoimmunity and cancer." (PMID 29988591, 2018). "Vitamin D promotes autophagy (ATG16L1 in autoimmune disorders like inflammatory bowel disorder) and suppresses pro-inflammatory pathways (such as p38 MAPK-mediated signaling pathway, prostaglandin pathway, nuclear factor kappa B signaling pathway)." (PMID 29988591, 2018).
bacterial sepsis (1 paper, 2014). "We did observe a trend suggestive of a lower likelihood of bacterial sepsis (OR 0.47, 95% CI: 0.04-5.26, p = 0.54) in patients with the minor allele of ATG16L1 (rs2241880)." (PMID 24465786, 2014).
cataract (1 paper, 2024). Partial or complete opacity of the crystalline lens of one or both eyes that decreases visual acuity and eventually results in blindness. "We found that stabilizing ATG16L1 by attenuating its ubiquitination-dependent degradation could promote autophagy and alleviate the cataract phenotype in connexin 50 (cx50)-deficient zebrafish 4, a typical cataract model with a defective autophagy process." (PMID 38994020, 2024). "A significant finding of our study is that excessive degradation of ATG16L1 through the UPS, catalyzed by the E3 ubiquitin ligase gigaxonin, disrupts autophagy in the cx50-deficient cataract model." (PMID 38994020, 2024). "Additionally, we discovered that riboflavin could regulate ATG16L1 ubiquitination, promoting autophagy and reducing lens opacity in various autophagy-related cataract models, including cx50-deficient zebrafish, H2O2-induced cataract zebrafish, and cold-induced cataract rat models." (PMID 38994020, 2024).
cervical carcinoma (1 paper, 2018). A carcinoma arising from either the exocervical squamous epithelium or the endocervical glandular epithelium. "Furthermore, ATG16L1, an autophagy protein, has recently been reported to participate in the IFN-γ-induced antiparasite response in a HeLa cervical carcinoma cell line." (PMID 30301855, 2018).
coronary aneurysm (1 paper, 2023). Abnormal balloon- or sac-like dilatation in the wall of coronary vessels. "It has even been shown that resveratrol increases the expression of ATG16L1 and LC3II by inducing autophagy, thus enhancing the anti-inflammatory effect of human coronary endothelial cells and even preventing the development of coronary aneurysms." (PMID 38114939, 2023).
dengue virus infection (1 paper, 2024). "Further differentiation of these donors based on their genotype revealed that the dengue virus infection levels in genotyped DCs were relatively higher in ATG16L1 rs6861(TT) donors as compared to ATG16L1 rs6861(CC)." (PMID 38863700, 2024). "Notably, the knock-down of either ATG5 or ATG16L1, essential autophagy molecules for autophagosome formation, led to a reduction in dengue virus infection of DCs." (PMID 38863700, 2024).
dry eye (1 paper, 2025). "The role of autophagy in dry eye is inherently complex; it can be protective when appropriately activated, yet detrimental when excessive or defective, as seen in disease-associated ATG16L1 polymorphisms." (PMID 41516297, 2025).
dysplasia (1 paper, 2022). A usually neoplastic transformation of the cell, associated with altered architectural tissue patterns. "Overall, these results suggest that mild (OLGIM I–II) and severe (i.e. OLGIM stage III–IV, dysplasia and GC) disease stages are not similarly affected by ATG16L1 rs2241880." (PMID 34965181, 2022).
endotoxemia (1 paper, 2015). "For instance, macrophages deficient in the autophagy protein Atg16L1 could produce inflammatory cytokines after LPS stimulation, suggesting that autophagy plays an important role in regulation of endotoxemia." (PMID 25625512, 2015).
esophageal adenocarcinoma (1 paper, 2023). A malignant tumor with glandular differentiation arising predominantly from Barrett mucosa in the lower third of the esophagus. "Upregulation of NOD2 expression increased the autophagy level of esophageal adenocarcinoma cells via ATG16L1." (PMID 36316517, 2023). "NOD2 can activate autophagy in esophageal adenocarcinoma cells through the ATG16L1 pathway and inhibit cell proliferation." (PMID 36316517, 2023).
experimental autoimmune encephalomyelitis (1 paper, 2025). An autoimmune demyelinating disease of the central nervous system that is produced experimentally in animals by the injection of homogenized brain or spinal cord in Freund's adjuvant. "Autophagy mediated by ATG16L1 in microglia ameliorates central nervous system inflammation and alleviates inflammatory responses and clinical symptoms of experimental autoimmune encephalomyelitis." (PMID 40211890, 2025).
fungal infection (1 paper, 2025). "In the context of fungal infection, ATG5 and ATG16L1 contribute to plasma membrane repair through lysosomal exocytosis, safeguarding epithelial cells against Candida albicans (C. albicans)." (PMID 40529614, 2025).